CCL4 (C-C motif chemokine ligand 4)
Diseases named in the same sentence as CCL4 in open-access papers (continued):
Sharing a sentence is not in itself a finding about the gene and the disease.
tumor (continued). "DC recruitment and subsequent T cell activation depend heavily on the production of chemokine CCL4 by tumor cells." (PMID 40429961, 2025). "Like CXCL10 and CXCL11, CCL3 and CCL4 have been attributed both tumor-promoting and anti-tumor effects." (PMID 40895532, 2025). "DGE analysis revealed that liver Tregs, compared to tumor and PBMC Tregs, had higher expression of key genes linked to Treg recruitment and immune suppression (e.g., CXCR3, CCL3, CCL4, and CCL5)." (PMID 40848148, 2025). "For instance, tumours with active β‐catenin signalling have reduced CCL4 production, leading to decreased intratumoural cDC1 infiltration and increased tumour growth." (PMID 40878038, 2025). "NF-κB alters the tumor microenvironment by modulating the secretion of cytokines and chemokines (GDF15, CCL3, and CCL4), promoting tumor cell survival and drug resistance." (PMID 40760228, 2025). "Following induction with DEN and CCL4, we observed significantly reduced tumor size and number in the livers of Nsun5‐KO mice compared to wild‐type mice, confirming the involvement of NSUN5 in HCC malignancy." (PMID 39531371, 2025). "We engineered armed Muc16/CA-125-directed CAR-T cells with cognate receptors for CCL2 and CCL4 and showed significant in vitro and in vivo tumor-directed trafficking." (PMID 41424784, 2025). "In contrast, high levels of CCL4 expression in ESCCs were correlated with a more favorable prognosis, suggesting a role in the recruitment of tumor-infiltrating CD8+ T lymphocytes and influencing the cancer microenvironment." (PMID 40092701, 2025). "To determine the subset of myeloid cells (CD45+CD11b+) in HCC, we analyzed 24 DEN/CCL4-induced spontaneous murine tumor tissues using mass cytometry by time of flight (CyTOF)." (PMID 40523887, 2025). "In human and mouse tumor models, beta-catenin-positive tumors suppress CCL4 expression to prevent cDC1 migration into the TME and promote tumor growth." (PMID 41176596, 2025). "Tumor microenvironment (TME) soluble mediator (Ccl2, Ccl3, Ccl4, Ccl5) and tumor cell marker (NeuN, Gpr17) RNA expression was quantitated by qRT-PCR." (PMID 41497446, 2025). "Taken together, the increased expression of endothelial Ccl2, Ccl3, and Ccl4 is necessary for leukocyte transmigration into the lung tissue in the context of virus- or bacteria-induced inflammation, autoinflammation, and tumor-promoting metastasis." (PMID 40111902, 2025). "CCL4 was identified as part of a four-chemokine expression signature for tumor samples, c-score, that can identify potential response to ICI treatments across several solid cancer types." (PMID 40989699, 2025). "Because CCL3, CCL4, and CCL5 signal through the CCR5 receptor, we next evaluated LLC tumor growth in CD8+ T cell–sufficient and –deficient mice treated with the FDA-approved CCR5 antagonist, maraviroc." (PMID 40553564, 2025). "In “cold” tumours, β-catenin signalling suppresses CCL4 transcription via activation of the transcription factor ATF3, thus impairing CD103+ DC recruitment and the associated T-cell infiltration." (PMID 40361472, 2025). "These molecules likely contribute to anti‐tumour immunity through distinct mechanisms—CD40 by enhancing dendritic cell activation and cytotoxic T cell responses, and CCL4 by potentially recruiting anti‐tumour immune cells to the tumour microenvironment." (PMID 40682474, 2025). "HCC: The induction of tumor cells to secrete the chemokine CCL4 recruits cytotoxic CD8+ T cells, thereby enhancing therapeutic efficacy." (PMID 40161377, 2025). "Nevertheless, while CCL5 became a more dominant ligand for CCR5 in the KPC-4545 tumor, CCL4 remained a dominant ligand for CCR5 and CXCL12, CXCL10, and CXCL16 arose as major ligands for different receptors in the KPC-3403 model following anti-IL-1β treatment." (PMID 39948655, 2025).
tumor (continued). "As such, interruption of these interdependent nodes resulted in inhibition of paracrine factors that attract T cells (Ccl2, Ccl3) and those important for TAM support of tumor growth (Ccl4, Ccl5)." (PMID 41497446, 2025). "Additional chemo-/cytokine analyses from co-culture supernatants of THP-1-macrophages and pre-treated tumor cells show an increased inflammatory response upon combination treatment, e.g. for chemoattractants CCL4 or CCL5." (PMID 38357194, 2024). "In the context of NPC, CCL3 or CCL4 can be expressed by malignant cells and tumor vascular endothelial cells." (PMID 39483474, 2024). "Other cells in the TME, such as mesenchymal fibroblasts and vascular endothelial cells, are also affected by CCL4, contributing to tumor growth." (PMID 39011399, 2024). "Higher levels of CCL2 and CCL4 in the tumor tissue of lung adenocarcinoma patients predicted unfavorable survival rates." (PMID 38928238, 2024). "Act-MG-1, based on expressing MHC-II, remarkably upregulated a series of transcription factors and cytokines (Ccl3, Ccl4, Jun, Junb, and Jund), indicating that this cluster of cells was a type of active microglia that can quickly respond to tumor stimulation." (PMID 39867913, 2024). "IFNs can modulate the TME by upregulating the secretion of the chemokine CCL4 from tumor cells or inducing a high-glucose microenvironment that promotes the transcription of T-cell costimulatory molecules." (PMID 39272910, 2024). "The release of CCL4 aids in tumor invasion, IL10 plays a role in immunosuppression, and THBD contributes to enhanced resistance to TMZ." (PMID 38832259, 2024). "Studies have shown that CCL4 can enhance tumor growth by attracting factors that promote tumorigenesis, and it also interacts with fibroblasts and endothelial cells to create a tumor microenvironment that supports tumor development." (PMID 39364412, 2024). "CCL4 can play an important but context-dependent and potentially contradictory role in the tumor microenvironment." (PMID 38712065, 2024). "Concurrently, neutrophils exhibiting high expression of CCL4 (CCL4_NEU) were specifically present during both tumor and metastatic stages." (PMID 39684426, 2024). "Consistent with the enhanced tumor suppression following ST bsAb treatment, the level of proinflammatory cytokines such as IL‐10 and CCL4 that inhibit anti‐tumor immunity was significantly decreased." (PMID 39553435, 2024). "Chemokines CCL5 and CCL4 have been associated with the modulation of TIME, particularly with respect to immune cell infiltration and tumor progression." (PMID 39001353, 2024). "The evidence suggested that ID1 inhibits the transcription of SerpinB2 and CCL4 in macrophages to promote tumor immune evasion and augment the tumor-initiating capacity of CRC cells, ultimately resulting in aggravated tumor growth and metastasis." (PMID 37996458, 2023). "Based on scRNA-seq results, we conducted mIF staining of T cells (CD3, CD4 and CD8), macrophages (CD68) and CCL4, which further indicated the differential distribution of immune cells between tumor thrombus and primary tumor." (PMID 37244923, 2023). "recently reported that in vivo eliminating the pro‐tumour TANs, mainly CCL4+ or PDL1+ subtypes, by anti‐Ly6G antibodies attenuated liver tumour growth in mice models." (PMID 37491740, 2023). "In this context, cytokines secreted from tumor and stroma cells, such as IL-10, as well as chemokines like CCL4, play a crucial role in shaping the immune TME in a tumor-promoting manner." (PMID 36982422, 2023). "Data suggest that tumor-cell-derived CCL4 promotes BC metastasis by prompting CCR5-expressing fibroblasts to express connective tissue growth factor." (PMID 37373025, 2023). "Chemokine ligand 4 (CCL4), which plays a critical role in tumor immune cell infiltration, was also significantly induced in the combination group." (PMID 37040183, 2023).
tumor (continued). "Diethylnitrosamine (DEN)‐CCL4 mouse liver tumour and the xenograft tumour models were used to evaluate the function of KDM6A in HCC progression." (PMID 37846441, 2023). "For example, our recent study published in Nature in 2022 demonstrated that CCL4+ TAN promotes tumor growth by recruiting tumor-associated macrophages, whereas PD-L1+ TANs promote tumor growth by inhibiting the killing function of CD8+ T cells." (PMID 37184030, 2023). "The S100A12+, ISG15+ and TXNIP+ subtypes are found in peripheral blood, the ELL2+ and PTGS2+ mainly in adjacent liver and the MMP8+, APOA2+, CD74+, IFIT1+, SPP1+ and CCL4+ predominantly located in the tumour." (PMID 37534829, 2023). "However, there is a paucity of research on the relationship between CCL4 levels and cancer susceptibility, possibly because it is difficult to measure CCL4 levels in the “carcinogenic niche,” which comprises inflammatory cells and their released cytokines in the tumor microenvironment." (PMID 37593100, 2023). "The six HCC TAN clusters; MMP8+, APOA2+, CD74+, IFIT1+, SPP1+ and CCL4+ can be characterised by predicted function and role in tumour development." (PMID 37534829, 2023). "CCL4, among other effects, recruits dendritic cells from lymph nodes, a critical step to reactivate an immune response against a tumor." (PMID 37958430, 2023). "CCL4 is essential for inflammation, tumorigenesis, and other immune responses, particularly tumor growth, metastasis, angiogenesis, and invasion, thus making it closely related to the pathogenesis of various cancers." (PMID 37593100, 2023). "The inhibitory effects of Id1 deletion in TAMs on both tumor growth and liver metastasis were completely abrogated when Ccl4 and Serpinb2 were depleted simultaneously." (PMID 37996458, 2023). "β-catenin promotes tumour development by regulating the expression of immune escape-related molecules (CCL4, CD47 and PD-L1) through transcription factors (MYC, TCF/LEF, NF-κβ, SNAI1, etc.)." (PMID 36646807, 2023). "It has also been shown, consistent with our findings, that high levels of chemokines CCL4, CCL22, and CCL28 in pre-treatment tumor specimens were associated with worse patient overall survival after immunotherapy in RCC." (PMID 38067341, 2023). "In this study, we identified an immunostimulatory TME in OS tumor thrombus with enriched TAM-M1 overexpressing CCL4 as well as elevated IFN-γ and TGF-β signalings." (PMID 37244923, 2023). "Further multiplexed immunofluorescence staining of the CD3/CD4/CD8A/CD68/CCL4 markers validates the immune-activated state in the tumor thrombus samples." (PMID 37244923, 2023). "CCL4 interaction with CCR5 can enhance the anti-tumor immune effect by making γδT cells enter cancer tissues from peripheral blood." (PMID 37593100, 2023). "Intravenous administration of CBD-CCL4 (collagen-binding domain (CBD) of von Willebrand factor) increases tumor localization of CCL4 and thereby recruits CD8+ T cells and CD103+ DCs." (PMID 37759462, 2023). "PEGylated IFN-α can also upregulate the chemokine CCL4 secreted by tumor cells and consequently recruit cytotoxic CD8+ T cells to infiltrate the HCC microenvironment, facilitating an improvement in the antitumor effect induced by anti-PD1 treatment." (PMID 38203603, 2023). "Further, CXCL9 was positively related to CCL4, CCL5, CXCL10, and CXCL11 in UCEC, which are associated with DC, NK, and T cell recruitment and play an essential role in suppressing tumor growth and improving prognosis." (PMID 36845675, 2023). "In a melanoma mouse model, the decrease of CCL4 secretion by tumor cells—following the activation of the β-catenin/Wnt pathway—inhibits cDC1 recruitment into the tumor site and leads to a decrease of the subsequent T-cell infiltration." (PMID 37190135, 2023). "In line with this, enrichment of high PD-L1 expressing IFIT1+, SPP1+ and CCL4+ TANs in HCC tumours correlated with a poorer prognosis indicating a pro-tumour role for these clusters." (PMID 37534829, 2023).
tumor (continued). "Several lines of evidence indicate that CCL4 can enhance tumor immunity by recruiting cytolytic lymphocytes and macrophages with phagocytic ability." (PMID 37041527, 2023). "From the immune response regulation aspect, 20 upregulated genes encoding chemokines with log2FC > 1.5 were selected, among which Ccl3, Ccl4, Cxcl9 and Cxcl16 shared with both tumor suppressive roles and effects in promotion of T cell infiltration 33–36." (PMID 37996458, 2023). "We then confirmed the in vivo effect of SCD1 inhibition on CCL4 production in tumor cells using mice implanted with DsRed-labeled MC38 tumors." (PMID 35793868, 2022). "CD103+ cDC1s are recruited to the tumor site by chemokines such as CCL4 and CCL5 secreted by tumor cells." (PMID 36275666, 2022). "Another group exploited a different strategy to deliver the DC-chemoattractant CCL4 into the tumor microenvironment." (PMID 35626062, 2022). "In vitro and in vivo studies demonstrated that CCL4 promotes tumor growth by upregulating the expression of VEGF-A, which affected the STAT3 signaling pathway in EC cells." (PMID 35626056, 2022). "In this study, the SCD1 inhibitor enhanced CCL4 production by cancer cells and by tumor-infiltrating CD8+ T cells." (PMID 35793868, 2022). "It has been shown that active β-catenin in TME induces low CCL4 expression, leading to a significant reduction of cDC1 infiltrate and consequently an increase in tumor growth." (PMID 35784290, 2022). "Dysregulation of the Wnt/β-catenin pathway reduces intratumoral D103+ DC numbers via suppression of CCL4 secretion in tumor cells (a chemokine that attracts DCs to infiltrate the tumor), thus presenting tumor-specific T cells priming." (PMID 36157510, 2022). "We found that myeloid cells from two clusters (aMΦ, bMΦ), characterized by the expression of tumor-associated macrophage genes (CD163, CCL4, APOE, and HLA-DRA) were strongly connected to the CD8+ exhausted and CD4+ Th1 T cell clusters." (PMID 35177622, 2022). "SLC7A1 not only participates in the metabolic remodelling of free amino acids in EOC cells but also inhibits the expression of the CCL4 molecule, which is closely related to the immune infiltration microenvironment of the tumor." (PMID 36131790, 2022). "Instead of injecting a viral-vector into the tumor directly, a fusion protein consisting of CCL4 and the collagen-binding domain (CBD) of von Willebrand factor were administered intravenously." (PMID 35626062, 2022). "HCC mouse model was then established using diethylnitrosamine (DEN)/CCl4 consisting of the injection of 25 mg/kg of DEN, followed by intraperitoneal injection of CCL4 for 12 weeks as a tumor promoter, and the tumor burden was analyzed after 12 weeks." (PMID 36438486, 2022). "In IV stage of the tumor’s advancement, statistically lower concentrations of CCL4 were demonstrated compared to the control group." (PMID 35407400, 2022). "Regulatory T cells (Treg), a sub-population of CD4+ T cells capable of downregulating anti-tumor immune responses, are induced by MDSC in the periphery and are attracted to the tumor site by secretion of the chemokines CCL4 and CCL5." (PMID 35455309, 2022). "These chemokines can be secreted by the tumor itself (e.g., CCL4, CCL5, XCL1) or by other infiltrating immune cells." (PMID 36230990, 2022). "Tumor-infiltrating basophils produce CCL3 and CCL4 to promote the recruitment of CD8+ T cells into the tumor microenvironment enhancing tumor rejection." (PMID 35693800, 2022). "Results support that TGF-β, MMP9, VEGF, and CCL4 are all significantly highly expressed in tumor samples." (PMID 35299868, 2022). "With the results of the increased CCL4 production by SCD1 knockdown tumor cells, these results suggested the immunoresistant role of SCD1 in tumor cells." (PMID 35793868, 2022).
tumor (continued). "The interaction of neutrophils and HNSCC/OSCC cells was found to enhance the chemotaxis of neutrophils to the TME and secretion of MMP-9 and CCL4 by neutrophils, triggering further recruitment and aiding tumor progression." (PMID 35784290, 2022). "MMP9, VEGF, and CCL4 were found to be employed by neutrophils to promote tumor development, and our study verified them to be upregulated in ccRCC." (PMID 35299868, 2022). "Secondly, the decreased secretion of the immune cell chemokine CCL4 in genetically engineered mouse models with conditionally expressing β-catenin resulted in inadequate recruitment of DCs and promoted tumor growth." (PMID 36358276, 2022). "Systemic administration of a SCD1 inhibitor in mouse tumor models enhanced production of CCL4 by cancer cells through reduction of Wnt/β-catenin signaling and by CD8+ effector T cells through reduction of endoplasmic reticulum stress." (PMID 35793868, 2022). "Consistent with previous reports, CCR8 is hyperexpressed on Tregs, and its ligand, CCL4, secreted by M2 macrophages, has been demonstrated to recruit Tregs to the tumor niche in other cancers." (PMID 35562760, 2022). "Fusion protein consisting of chemokine CCL4 and collagen-binding domain was applied to recruit TILs to improve the antitumor immunity of anti-PD-L1 monotherapy in multiple tumor models." (PMID 36544785, 2022). "CCL4 belongs to the proinflammatory C-C subfamily and acts in inflammation, immune regulation, and tumor progression." (PMID 35296026, 2022). "Higher production of CCL4 by tumor-infiltrating T cells was observed compared with cancer cells on a per-cell basis." (PMID 35793868, 2022). "We found that HPV+ tumour cells expressed higher levels of CCL4 by analysis of their cell-to-cell interactions and that this expression was highly correlated with CD8+ T cells and immune checkpoint molecules." (PMID 36420261, 2022). "In non-small cell lung cancers (NSCLC) with high neoantigen load, β-catenin expression was associated with low levels of CCL4 in the TME, resulting in reduced DC infiltration into the tumor." (PMID 36275666, 2022). "Correspondingly, we found that HPV+ tumour cells expressed higher levels of CCL4, and these were highly correlated with CD8+ T cells infiltration and immune checkpoint molecules." (PMID 36420261, 2022). "In some situations, CCL4 can enhance tumour immunity by recruiting cytolytic lymphocytes and macrophages with phagocytic ability." (PMID 35865633, 2022). "In DsRed-labeled MC38-bearing mice, the expression of CCL4 was found to be significantly higher in tumor-infiltrating CD8+ T cells on a per cell basis than in tumor cells, and it was increased by treatment with the SCD1 inhibitor." (PMID 35793868, 2022). "Although the difference between SSMs from tumor-draining and non-draining lymph nodes was not as stark as in the case of FcgR1 and FcgR4, we measured increased co-localization of MMP14 and CCL4 with CD169+ SSMs in tumor-draining nodes." (PMID 34168645, 2021). "Several of these chemokines, including CCL21, CCL2, and CCL4, recruit anti-tumor leukocytes but can also recruit pro-tumor leukocytes such as Tregs, depending on the type of malignancy." (PMID 34316327, 2021). "Circulatory and tumor associated levels of CCR5 and its cognate ligands (CCL3, CCL4, CCL5) were analyzed by ELISA, qRT-PCR and immunohistochemistry." (PMID 32902795, 2021). "The results showed increased NE and EPI levels in serum in both wild-type mice and DEN + CCL4-induced tumor-bearing mice in the EE housing condition." (PMID 34593796, 2021). "Correspondingly, CCL4 gene transfer has inhibited tumor growth and prolonged the survival of tumor-bearing mice." (PMID 34885960, 2021). "In tumor lesions, CCL4 expression was negatively correlated with the expression of the NPTX2, which implied that NPTX2 potentially participates in immunoregulation in the tumor microenvironment." (PMID 34258887, 2021).